RASGRP1 (RAS guanyl releasing protein 1)
Diseases named in the same sentence as RASGRP1 in open-access papers (continued):
Sharing a sentence is not in itself a finding about the gene and the disease.
Insulin resistance (1 paper, 2020). Increased resistance towards insulin, that is, diminished effectiveness of insulin in reducing blood glucose levels. "Three SNPs were associated with increased insulin resistance risk with adjusting for covariates, including 5q11.2-rs4432842 (OR = 1.23, 95% CI: 1.04–1.45), RASGRP1-rs7403531 (OR = 1.35, 95% CI: 1.13–1.62), SEC16B-rs574367 (OR = 1.34, 95% CI: 1.07–1.67)." (PMID 32260174, 2020). "Among the 64 susceptible loci we examined, RASGRP1-rs7403531, ANK1-rs516946, and SEC16B-rs574367 had associations with insulin resistance." (PMID 32260174, 2020).
mastitis (1 paper, 2023). Inflammation of breast tissue during lactation or postpartum due to an obstructed duct or infection. "Pathogen challenge causes RASGRP1 to express differently, suggesting a potential role in ruminant mastitis." (PMID 36669036, 2023).
mastocytoma (1 paper, 2011). A localized tumor composed of sheets of mast cells without atypia. "The nature of RasGRP1 localization and mobilization in the P815.B7 cell may be an interesting area of future study and could potentially occur through reverse B7 signaling in this mastocytoma-derived cell line, as has been demonstrated previously in dendritic cells." (PMID 21949793, 2011).
Noonan syndrome (1 paper, 2017). Noonan Syndrome (NS) is characterized by short stature, typical facial dysmorphism and congenital heart defects. "Four of the proteins are linked to various forms of the Noonan syndrome (CBL, MAP2K1, RAF1 and SOS), 5 to various types of tumors (MAPK1, PRKCQ, ABL1, GRAP2 and RAS) and one to an autoimmune disorder (RASGRP1)." (PMID 28448599, 2017).
osteoporosis (1 paper, 2023). A condition of reduced bone mass, with decreased cortical thickness and a decrease in the number and size of the trabeculae of cancellous bone (but normal chemical composition), resulting in increased fracture incidence. "Five genes remained after the LASSO feature selection, and the formula for the osteoporosis risk score (ORS) was established as follows: ORS = 33.991 - 2.272 * ABCD2 - 6.201* RORA + 2.237 * ITK - 1.100 * CAMK4 + 0.466 * RASGRP1." (PMID 37051201, 2023).
Sepsis (1 paper, 2023). Sepsis is defined as life-threatening organ dysfunction caused by a dysregulated host response to infection. "GNLY, GZMB, PRF1, and RASGRP1, which are lysosome-related genes, are closely linked to the prognosis of sepsis and could potentially serve as novel research targets for sepsis, offering valuable insights for the development of lysosome-targeted therapy." (PMID 38057716, 2023). "The analysis revealed that GNLY, GZMB, PRF1, and RASGRP1 exhibited high expression levels in the normal control group, while their expression was low in the sepsis group." (PMID 38057716, 2023). "GNLY, GZMB, PRF1, and RASGRP1 are lysosome-related genes that are closely related to the prognosis of sepsis, and may be used as new research targets for sepsis and provide direction for lysosome-targeted therapy." (PMID 38057716, 2023). "In conclusion, the genes GNLY, GZMB, PRF1, and RASGRP1 exhibited significant upregulation in the normal control group and downregulation in the sepsis group, thereby displaying a positive correlation with the prognosis of sepsis patients." (PMID 38057716, 2023). "Survival analysis screened four genes positively correlated with sepsis prognosis, namely GNLY, GZMB, PRF1 and RASGRP1." (PMID 38057716, 2023). "Notably, the analysis revealed that GNLY, GZMB, PRF1, and RASGRP1 exhibited significantly higher expression levels in the normal control group compared to the sepsis group (P<0.05)." (PMID 38057716, 2023).
Splenomegaly (1 paper, 2012). Abnormal increased size of the spleen. "Although RasGRP1d/d mice did not have as severe defects in T cell development as RasGRP1−/− mice, they exhibited splenomegaly at ∼3–4 months of age." (PMID 22719950, 2012).
thyroid (1 paper, 2013). "In addition, RASGRP1-linked SNVs have been associated with autoimmune diabetes and thyroid disease." (PMID 24336796, 2013).
cancer (21 papers, 2013 to 2025). A tumor composed of atypical neoplastic, often pleomorphic cells that invade other tissues. "Examination of the EGFR signalling pathway shows that RasGRP1 inhibits inflammation-associated cancer cell growth by disrupting the EGFR-SOS1-Ras-AKT signalling pathway." (PMID 36385095, 2022). "Here, we report that Ras guanine nucleotide-releasing protein 1 (RasGRP1) is a bifunctional regulator that promotes acute inflammation and inhibits inflammation-associated cancer." (PMID 36385095, 2022). "Our study demonstrated that RasGRP1 is a key regulator that promotes production of the proinflammtory cytokine IL-6 and decreases the probability of inflammation-associated cancer developing during acute inflammation." (PMID 36385095, 2022). "Here the authors propose the protein and mRNA of RasGRP1 have opposing functions by promoting IL-6 mediated acute inflammation and inhibiting inflammation-associated cancer through mRNA and protein mechanisms respectively." (PMID 36385095, 2022). "As a bifunctional regulator that promotes acute inflammation and inhibits inflammation-associated cancer, RASGRP1 overexpression may suppress cancer cell growth and lead to a better prognosis in cancer patients." (PMID 38495494, 2024). "Under physiological conditions, especially during an acute inflammatory response, RasGRP1 may be important in regulating the inflammatory response and decreasing the probability that inflammation-associated cancer will develop." (PMID 36385095, 2022). "However, further investigation may be required to understand whether RasGRP1-mediated EGFR-SOS1-Ras-ERK or EGFR-SOS1-Ras-AKT signalling inhibition is a general mechanism that affects other inflammation-associated cancers." (PMID 36385095, 2022). "To verify the selected DEM (hsa-miR-21-5p), DEL (MIR99AHG) and 5 DEGs (RECK, TIMP3, EHD1, ERG and RASGRP1), we collected sequencing data from several cancer and normal tissues to explore the expression levels of these RNAs." (PMID 38495494, 2024). "Cong Wang has unveiled, through experimentation and observation, the dual role of RASGRP1 in regulating acute inflammatory responses and inhibiting inflammation-related cancers and its promising prognostic value." (PMID 38751445, 2024). "Much of the work done on RasGRP1 within the realms of immunology and cancer research in the last 5 years has focused on three areas." (PMID 36675167, 2023). "Given its position at the crossroad of cell development, inflammation, and cancer, RASGRP1 has garnered interest from numerous disciplines." (PMID 36675167, 2023). "A broad review of all RasGEFs in various cell types is beyond the scope of this focused review of RasGRP1 in cancer; however, we direct the reader to previous reviews." (PMID 36675167, 2023). "The third area is the mechanism by which RasGRP1 serves as a tumor suppressor in certain cancer models." (PMID 36675167, 2023). "Given the importance of RasGRP1 in cell development, it is unsurprising that it is expressed in numerous cancers and plays a role in oncogenesis." (PMID 36675167, 2023). "It is evident that the relevance of RasGRP1 reaches beyond the development and function of immune cells and homeostasis and cancer." (PMID 36675167, 2023). "In this study, we showed that RasGRP1 has an important function in regulating the acute inflammatory response and cancer." (PMID 36385095, 2022). "In cancer T cells, expression of CD44 has been linked to enhanced mTOR activation as the result of RasGRP1 mutations." (PMID 29180720, 2017). "RASGRP1 (RAS guanyl releasing protein 1), a bi-functional regulator that promotes acute inflammation and inhibits inflammation-associated cancers, can inhibit the growth of inflammation-associated tumors and activate inflammatory response by sponging let-7a to promote IL-6 expression." (PMID 40861815, 2025). "IL-6 and RasGRP1 have been shown to have important functions during inflammation and cancer." (PMID 36385095, 2022).
cancer (continued). "To investigate whether the RasGRP1 protein exerts an inhibitory effect on other cancers, we examined the effect of RasGRP1 gene expression on the survival of cancer patients with one of the multiple types of cancer." (PMID 36385095, 2022). "One of the properties Tipifarnib has is the inhibition of RAS farnesylation and the upregulation of RASGRP1 might characterize cancer cells which rely on RAS signaling." (PMID 31063487, 2019). "For more detailed reading on RasGRP1’s role in cancer we refer you to a different review." (PMID 24027568, 2013). "These last two emerging areas point to the idea that RasGRP1 cannot simply be described as an “oncogene” or its overexpression as a negative indicator, but rather that its role is cancer- and model-dependent." (PMID 36675167, 2023). "The results showed that high expression of TSLP, RASGRP1, APOD, and PTGER3 was correlated with cancer cell drug sensitivity to a variety of chemotherapeutic drugs, especially APOD, which was highly correlated with drug sensitivity to ARQ-680, SB-590885, PLX-4720, vemurafenib, and others." (PMID 36467500, 2022).
tumor (16 papers, 2012 to 2025). "The transformation of thymocytes requires the overexpression of RasGRP1 and a cooperating oncogene or knockout of a tumor suppressor." (PMID 36675167, 2023). "Tumour patients with high RasGRP1 expression have better clinical outcomes than those with low RasGRP1 expression." (PMID 36385095, 2022). "To ascertain the role of RasGRP1, we used lentivirus to overexpress RasGRP1 in Huh 7 cells and found that RasGRP1 overexpression significantly inhibited the tumour-promoting effect of IL-6." (PMID 36385095, 2022). "The RasGRP1 IHC score for the tumour samples with upregulated RasGRP1 expression was higher than that in tumour samples with downregulated RasGRP1 expression." (PMID 36385095, 2022). "Results showed significant upregulated expression of certain genes like Hgf, Hmga1, Rasgrp1, Sh2b2, Socs1, Socs2, and Socs3 in WT mice tumor compared to its ChREBP systemic knockout tumor." (PMID 34685767, 2021). "Considering that acute inflammation rarely leads to tumorigenesis, this study suggests that RasGRP1 may be an important bifunctional regulator of the acute inflammatory response and tumour growth." (PMID 36385095, 2022). "Indeed, this was the orientation bias observed for integrations into both Ccnd1 and Rasgrp1 in TP-16 tumor DNA." (PMID 31815961, 2019). "Importantly, like I3A, the non-tumor promoting DAG analogue bryostatin 1 was shown to preferentially target RasGRP1 to internal membranes, compared to PMA." (PMID 23991094, 2013). "RASGRP1 has a dual regulatory role in tumor growth and the acute inflammatory response, and TNBC patients with higher expression of RASGRP1 have a better clinical prognosis, which was also confirmed in our study." (PMID 40746884, 2025). "Specifically, tumor tissues show increased expression of SERPINA1, RASGRP1, and CFB compared to normal tissues, whereas C1S, SERPINF2, and TLN2 display the opposite pattern." (PMID 38751445, 2024). "It demonstrated a notably elevated expression of SERPINA1, RASGRP1, and CFB in tumor tissues, while C1S and TLN2 showed significantly higher expression in normal tissues." (PMID 38751445, 2024). "Compared with group B, we found that less RASGRP1, VPS28, and RAS downstream proteins p-MEK1/2 and p-ERK1/2 were expressed in mice tumor sections of group G. Moreover, the group G had high levels of ERBIN expression." (PMID 38773970, 2024). "Additionally, when DEA was performed between tumor and normal tissues from the validation set, it could be seen that both genes were highly expressed in tumor tissues, but RASGRP1 was a differentially expressed gene, while ACAP1 was not." (PMID 32503630, 2020). "Notably, upregulated genes in relapsed SW837 xenograft tumor included MRAS, a homologue of the RAS family of GTPases37, and RasGRP1, a Ras GEF38,39, but not NRAS or HRAS." (PMID 39103541, 2024).
cardiovascular diseases (2 papers, 2014 to 2025). "These regions contain genes associated with calcium channels (CACNA1S), renin catalysis (REN), blood groups (ABO), apolipoprotein (APOA5), and cardiovascular diseases (RASGRP1)." (PMID 25519368, 2014).
mental illness (2 papers, 2016 to 2022). "Overall, we suggested RasGRP1 alteration in brain and in peripheral districts of the body in patients with this mental illness." (PMID 35204828, 2022).
neurological diseases (2 papers, 2020 to 2023). "Thus, to study whether and how Nurr1 and RasGRP1 are involved in inflammation signaling in the brain may be helpful to elucidate their potential roles in neurological disorders." (PMID 32612143, 2020).
infection (1 paper, 2016). The state of being infected such as from the introduction of a foreign agent such as serum, vaccine, antigenic substance or organism. "Several genes upstream of Ras-ERK signalling including Rasgrp1 and Rasgrf2, were expressed at higher levels in infected FoxO3a−/− macrophages, indicating that FoxO3a regulates the expression of these genes upon infection." (PMID 27599659, 2016).
RASGRP1 also shares sentences with these, for which no sentence is quoted: type 2 diabetes mellitus (4 papers); viral infection (3); lung adenocarcinoma (2); squamous cell carcinoma (2); acute kidney injury (1); alcohol dependence (1); atherosclerosis (1); autoimmune hemolytic anemia (1); autoimmune type 1 diabetes (1); bipolar disorder (1); blood cancer (1); cervical cancer (1); chronic kidney disease (1); genetic disorders (1); Huntington disease (1); hyperinsulinemic hypoglycemia (1); hypothyroidism (1); inflammatory bowel disease (1); lung carcinoma (1); lymphopenia (1); memory impairment (1); metabolic disease (1); multiple sclerosis (1); NK/T cell lymphoma (1); psychotic disorder (1); Stroke (1); triple-negative breast carcinoma (1); type 1 diabetes (1); uveal melanoma (1); Vasculopathy (1).
A further 1 disease shares a sentence with RASGRP1 in 1 paper.